RN7SL49P (RNA, 7SL, cytoplasmic 49, pseudogene)
Gene: Miscellaneous RNA gene on chromosome 13 (45,002,150 to 45,002,447, forward strand). Ensembl gene ENSG00000265802.
Homologues: Orthologues: chimpanzee Metazoa_SRP (98% identical), macaque Metazoa_SRP (94% identical). Paralogues in human: RN7SL1 (86% identical), RN7SL2 (85% identical), RN7SL3 (85% identical), RN7SL126P (82% identical), RN7SL113P (81% identical), RN7SL408P (81% identical), RN7SL664P (81% identical), RN7SL851P (81% identical), RN7SL464P (81% identical), RN7SL559P (81% identical), RN7SL18P (80% identical), RN7SL220P (80% identical), and 704 more.